MIR130B (microRNA 130b)
Synonyms: hsa-mir-130b; MIRN130B; mir-130b
Gene: MicroRNA gene on chromosome 22 (21,653,304 to 21,653,385, forward strand). Ensembl gene ENSG00000283871.
Diseases named in the same sentence as MIR130B in open-access papers:
MIR130B is named in the same sentence as 6 diseases in open-access papers, as found by Europe PMC text mining. Sharing a sentence is not in itself a finding about the gene and the disease. The quoted sentences say what the papers report.
gastric cancer (1 paper, 2021). A primary or metastatic malignant neoplasm involving the stomach. "Importantly, recent studies have documented, while responding to an H. pylori infection, the infiltration of a unique subset of PMN-MDSCs which express MIR130B, an endogenous short noncoding RNA, as well as TNF-α, known to contribute to immunotherapy-resistant gastric cancer." (PMID 34944780, 2021).
pancreatic cancer (1 paper, 2015). "MIR130B is down-regulated in pancreatic cancer tissues and its expression is a useful prognostic for pancreatic cancer patients." (PMID 26039411, 2015).
MIR130B also shares sentences with these, for which no sentence is quoted: colorectal cancer (1 paper); endometrial cancer (1); neoplastic diseases (1); schizophrenia (1).